CA6 (carbonic anhydrase 6)
Diseases named in the same sentence as CA6 in open-access papers:
CA6 is named in the same sentence as 47 diseases in open-access papers, as found by Europe PMC text mining. Sharing a sentence is not in itself a finding about the gene and the disease. The quoted sentences say what the papers report.
dental caries (19 papers, 2018 to 2024). The decay of a tooth, in which it becomes softened, discolored, and/or porous. "Instead, lower concentrations of salivary carbonic anhydrase 6 have been associated with dental caries and primary Sjögren’s syndrome, suggesting a potential divergence of its role in various oral health conditions." (PMID 37834046, 2023). "In conclusion, the results indicate that CA6 gene polymorphisms influence S. mutans colonization, tooth biofilm microbiota composition and risk of dental caries in Swedish adolescents." (PMID 30679524, 2019). "In conclusion, the results from the present study support that CA6 gene polymorphisms rs10864376 (T), rs3737665 (T), rs12138897 (G) and haploblock TTG of CA6 are associated with S. mutans colonization, overall microbiota composition and dental caries in Swedish adolescents." (PMID 30679524, 2019). "A recent study found associations between carbonic anhydrase VI (CA6), S. mutans colonization, tooth biofilm microbiota composition, and risk of dental caries." (PMID 34335772, 2021). "This study tested the hypothesis that variation in the CA6 gene is relevant to dental health and found that CA6 gene polymorphisms and haploblocks of CA6 were associated with S. mutans colonization, overall microbiota composition and dental caries in Swedish adolescents." (PMID 30679524, 2019). "High activity of carbonic anhydrase 6 in the saliva might induce biofilm formation and aid in the development of dental caries." (PMID 35613108, 2022). "The high expression level of carbonic anhydrase 6 may affect dental caries activity under stress conditions." (PMID 35613108, 2022).
Sjögren’s syndrome (11 papers, 2011 to 2023). "CA6 (gustin) and CA7 are both expressed in salivary glands and ameloblasts, and have been linked to Sjogren’s syndrome." (PMID 36404915, 2022). "Immunoglobulin A (IgA) anti-CA VI autoantibodies are frequently seen in patients with long-term Sjögren’s Syndrome (SS) and antibodies to SP1, CA6 and PSP gene products provide valuable markers for the diagnosis of primary and secondary SS." (PMID 35947329, 2022). "The current studies demonstrate that many patients with idiopathic dry eyes with or with out dry mouth have markers for early Sjogren’s syndrome, anti-SP1, anti-CA6 and anti-PSP." (PMID 28270126, 2017). "To elucidate the role of the tissue-specific autoantibodies (TSAs), i.e., anti-CA6, anti-SP1, and anti-PSP antibodies, we enrolled 137 pSS patients, 32 secondary Sjögren's syndrome (sSS) patients, and 127 healthy controls (HCs), whose serum and saliva samples were collected." (PMID 31205955, 2019).
breast carcinoma (8 papers, 2010 to 2024). "In our study we did not test expression of CA6 but women with a less active form of the CA6 gene (G allele) had an increased risk of breast cancer." (PMID 38687739, 2024). "For the CA6 gene, when evaluating the genotype, our results again showed associations with breast cancer risk which were in opposite direction from what we initially hypothesized." (PMID 38687739, 2024). "The level of CA6 showed a significant difference between breast cancer and healthy controls (n = 93)." (PMID 21217834, 2010). "Interestingly, the secreted CA6/Car6 is downregulated in the human breast cancer tissue but upregulated in the murine breast cancer tissue." (PMID 37098526, 2023). "To examine the relationship between risk of breast cancer and TAS2R38 and CA6 gene individually and for the joint genotype we ran logistic regression to obtain odds ratios for breast cancer status for individual diplotypes of the TAS2R38 and individual genotypes of the CA6 gene." (PMID 38687739, 2024). "Explanation of our results of significant association between rs2274333 and the increased risk of breast cancer for the non-tasters, may be related to other functions of the CA6 gene than taste perception, such as acid-base balance." (PMID 38687739, 2024). "Based on proteomic data from human biopsies, we additionally confirm the expression of cytosolic (CA1, CA2, CA3, CA13), mitochondrial (CA5β), and extracellular (CA4, CA6, CA9, CA12) carbonic anhydrases in breast cancer tissue." (PMID 37098526, 2023). "For the combined genes TAS2R38 and CA6, the genotype AVI/AVI+G* (non-tasters), relative to the reference group of PAV/*+A/A (tasters) showed a statistically significant association with breast cancer status (OR = 1.77;95% CI 1.47–2.74; p = 0.010)." (PMID 38687739, 2024). "Notably, elevated levels of CA6 and CA15-3 have been detected in the saliva of breast cancer patients." (PMID 37047335, 2023). "PSAT1, CA6 and CA9 are part of the Metabolic Pathways and affect the growth and migration of breast cancer cells MIR100 and MIR124-2 are two MicroRNAs within the same signaling pathway that induce apoptosis and cell cycle arrest in breast cancer cells through multiple genes." (PMID 38254021, 2024). "However, the function of CA6 gene in cancer is not known, although it has been observed that the secreted protein of CA6 gene is downregulated in the human breast cancer tissue and thus can also impact the pH homeostasis." (PMID 38687739, 2024). "Interestingly, CA6, which was validated in our study, was also discovered in this previous proteomic profiling study using saliva samples from non-invasive breast cancer patients (DCIS), indicating the potential of this biomarker for the early detection of breast cancer." (PMID 21217834, 2010).
dry eye (4 papers, 2015 to 2021). "This cross-sectional study demonstrated that anti-CA6 is seen in patients with severe aqueous-deficient dry eye." (PMID 30766890, 2019). "In patients with dry eyes and dry mouth but F = 0, increased expression of anti- CA6 was noted compared to the F <1 group (p = .032) or the F > 3 group (p = .006)." (PMID 25881294, 2015). "This retrospective study evaluated the clinical relevance of the three novel autoantibodies, anti-SP1, anti-CA6, and anti-PSP, in patients with clinically significant aqueous-deficient dry eye who were suspected of having an underlying autoimmune disease, particularly SS." (PMID 30766890, 2019). "We recently evaluated these antibodies in a small sample of dry eye patients in a prospective cross-sectional study and found that anti-CA6 was associated with severe aqueous-deficient dry eye indicating perhaps an early SS without positive traditional antibodies." (PMID 30766890, 2019). "In patients with only dry eyes, equal numbers of patients express either anti-SP1, anti-CA6 or anti-PSP with several patients expressing two or all three of these autoantibodies." (PMID 28270126, 2017). "The current studies were established to investigate the presence of anti-SP1, anti-CA6 and anti-PSP in a population of patients with dry eyes." (PMID 28270126, 2017). "Higher levels of anti-CA6 were also demonstrated in patients from the SICCA cohort who had significant dry eye and dry mouth but no lymphocytic focus." (PMID 30766890, 2019). "Antibodies to SP1, CA6 and PSP occur in some patients with idiopathic dry eyes." (PMID 28270126, 2017). "In patients with dry eyes and dry mouth and Schirmer’s tests 3 mm < SCH < 6 mm, anti-SP1 was the dominant autoantibody while in the patients with Schirmer’s tests < 3 mm, anti-CA6 was the dominant autoantibody." (PMID 28270126, 2017). "Interestingly, the University of Pennsylvania SICCA cohort study indicated anti-SP1 IgM and anti-PSP IgA as most prevalent, instead of anti-CA6, in SS-dry eye compared to non-SS dry eye." (PMID 34249010, 2021). "Similarly, in our previous report, we detected anti-CA6 antibodies in 43% of the patients who had significant dry eye but negative serology and biopsy (thus not fulfilling 2012 ACR classification criteria for SS)." (PMID 30766890, 2019).
Obesity (4 papers, 2017 to 2025). Accumulation of substantial excess body fat. "Nonetheless, we considered that two of them, CA6 (gustin) and chemerin, deserved further investigation because of the biological relevance to obesity and strong, consistent genetic association signals during the LCD." (PMID 29234017, 2017).
COVID-19 (3 papers, 2022 to 2023). A disease caused by infection with severe acute respiratory syndrome coronavirus 2. "We also showed the downregulation in cystatins and CA6 that can be involved in the sensory response to stimulus and possibly related to the presence of anosmia and dysgeusia during the COVID-19." (PMID 35760827, 2022).
colorectal cancer (2 papers, 2017 to 2024). A primary or metastatic malignant neoplasm that affects the colon or rectum. "Within the same study, the results showed that the combined G/A and G/G genotype (non-tasters) in CA6 gene reduced the risk of developing colorectal cancer (OR = 0.70; 95% CI 0.55–0.88, p = 0.008)." (PMID 38687739, 2024). "In the second study of colorectal cancer, the reported results for TAS2R38 and CA6 were opposite to our current observations, and congruent with our initial hypotheses." (PMID 38687739, 2024).
acinar cell carcinoma (1 paper, 2020). "CA6 is a specific marker for salivary gland serous acinar cells and acinar cell carcinoma (AciCC)." (PMID 33456371, 2020).
autoimmune disease (1 paper, 2019). A disorder resulting from loss of function or tissue destruction of an organ or multiple organs, arising from humoral or cellular immune responses of the individual to their own tissue constituents. "On the other hand, anti-CA6 was the most prevalent of the novel autoantibodies in patients without any known autoimmune disease and the only novel autoantibody associated with severe ocular surface staining (both corneal and conjunctival)." (PMID 30766890, 2019). "More importantly, anti-CA6 was more frequent in patients with no known autoimmune diseases at the time of the testing." (PMID 30766890, 2019). "Anti-PSP was the most frequently detected novel autoantibody in patients with primary SS (6/8, 75%), while anti-CA6 was the most commonly detected novel autoantibody in patients with other autoimmune diseases (5/10, 50%) and with no known autoimmune diseases (21/37, 57%)." (PMID 30766890, 2019).
co-infection (1 paper, 2022). "Recent studies also showed that EV71 and CA16 were the main pathogens of HFMD in Suzhou in 2017, and CA6 was the main pathogen of HFMD in 201846, and the co-infection of EV71 or Cox A16 and CA6 or CA10 was also found in Suzhou29." (PMID 35260706, 2022).
diabetes (1 paper, 2025). "Additionally, CXCL13, CA6, SDC1, and PTN demonstrated mediating effects in the association between Health Behaviors and outcomes such as diabetes, renal disease, and death." (PMID 41290610, 2025). "CXCL13, CA6, SDC1, and PTN, on the other hand, mediate the relationship between Health Behaviors and renal diseases, diabetes, and death." (PMID 41290610, 2025).
lung carcinoma (1 paper, 2014). "The two metabolic enzymes in the classifier, CNDP1 and CA6, are lower in the serum of lung cancer patients, perhaps in response to the low pH created by increased tumor glycolysis." (PMID 25114662, 2014).
myocardial infarction (1 paper, 2025). Gross necrosis of the myocardium, as a result of interruption of the blood supply to the area, as in coronary thrombosis. "The causal relationships revealed that NQO2 (1.047; 1.002–1.094; P = 0.042), CA6 (1.886; 1.015–1.162; P = 0.017), PTGDR (1.073; 1.012–1.137; P = 0.018), PTK2 (1.085; 1.002–1.176; P = 0.046), and CASP7 (1.080; 1.026–1.137; P = 0.003) were associated with high risk of myocardial infarction." (PMID 41573742, 2025).
ovarian carcinoma (1 paper, 2022). A malignant neoplasm originating from the surface ovarian epithelium. "The first clinical study on a Fab targeting carbonic anhydrase 6 (CA6) epitope of MUC1 reported the safety of this probe in an ovarian cancer patient, and the probe correctly reflected the low tumor expression of CA6 observed in IHC." (PMID 35836956, 2022).
parathyroid carcinoma (1 paper, 2012). "The frame shift mutation in Ca5 had been reported previously in HPT-JT syndrome and missense mutation in Ca6, frame shift mutation in Ca10 had been reported in sporadic parathyroid carcinoma." (PMID 23029104, 2012).
periodontitis (1 paper, 2023). An acute or chronic inflammatory process that affects the tissues that surround and support the teeth. "The authors of this study suspect that perhaps failure/impaired salivary hypoxia responses, as reflected by downstream carbonic anhydrase 6 production, might predispose individuals to adult periodontitis." (PMID 37834046, 2023).
psoriasis (1 paper, 2022). An autoimmune condition characterized by red, well-delineated plaques with silvery scales that are usually on the extensor surfaces and scalp. "The authors discovered four DEPs, namely kynureninase/KYNU, lectin galactoside-binding soluble 3-binding protein/LG3BP, and tryptase β2/TPSB2, and carbonic anhydrase 6/CA6, in the sera of psoriasis patients." (PMID 35327421, 2022).
rheumatoid arthritis (1 paper, 2014). A chronic, systemic autoimmune disorder characterized by inflammation in the synovial membranes and articular surfaces. "In unpublished studies, antibodies to Sp1 and CA6 were found in less than 5 percent of normal controls and patients with rheumatoid arthritis lacking secondary SS." (PMID 24885364, 2014).
cancer (8 papers, 2010 to 2024). A tumor composed of atypical neoplastic, often pleomorphic cells that invade other tissues. "In summary, the results from studies evaluating the association between the TAS2R38 and CA6 genes and the risk of cancer are inconsistent." (PMID 38687739, 2024). "Recent evidence has demonstrated that some cancer cell lines have over-elongated centrioles, which can promote CA6." (PMID 32681070, 2020). "The levels of CA6 and psoriasin between cancer and control samples showed significant differences (p = 0.012 and 0.014, respectively)." (PMID 21217834, 2010).
tumor (6 papers, 2014 to 2023). "In animal tumor models, the effective dosage of SAR566658 correlates with the expression of CA6, a MUC1-associated sialic acid glycoprotein." (PMID 37305567, 2023). "SAR566658 comprises the anti-CA6 antibody huDS6 conjugated to DM4, including tumor cell death through CA6 recognition." (PMID 37305567, 2023). "The ADC was called SAR566658 and it showed antitumor efficacy against CA6-positive human pancreas, cervix, bladder, and ovary in vivo tumor xenograft models, with a minimal effective dose correlating with CA6 expression as well as better efficacy than standard-of-care nontargeted tubulin binders." (PMID 33167508, 2020). "We measured CRC-related protein tumor markers by ECL immunoassays and constructed model CA6 for early diagnosis of colorectal lesions using the ANN algorithm." (PMID 37504084, 2023). "Results demonstrate that the false positive rate and false negative rate of the CA6 model were lower than those of conventional tumor markers." (PMID 37504084, 2023). "The proteins in our classifier are related to the biology of tumor growth and function to sustain proliferation and activate invasion (MMP7 and MMP12), and respond to oxidative stress and deregulation of cellular energetics (CNDP1 and CA6)." (PMID 25114662, 2014). "The CA6 model established by ANN provides a new and effective method for laboratory auxiliary diagnosis, which might be utilized for early colorectal lesion screening by incorporating more tumor markers with larger sample size." (PMID 37504084, 2023).
infection (5 papers, 2020 to 2026). The state of being infected such as from the introduction of a foreign agent such as serum, vaccine, antigenic substance or organism. "To determine whether the cytopathic effect caused by CA6 at 36 h post infection is similar to the cytopathic effect caused by EV71 at 24 h post infection, we performed morphology analysis." (PMID 32117097, 2020). "To investigate the anti-viral efficacy of C15 against CA6 in vivo, we established a lethal infection model using 1-day-old ICR mice." (PMID 39772852, 2025). "The results confirm CA6 infection induced necroptosis (Figure 3D2) compared to mock infection (Figure 3D1), and the increased expression of RIPK3 was visualized in necroptotic cells induced by CA6-infection (Figure 3D4) compared to mock-infection (Figure 3D3)." (PMID 32117097, 2020). "Finally, we analyzed CA6 virus production at 36 h post-infection." (PMID 32117097, 2020). "PF4 overexpression suppressed the replication of CA6 and EVD68 as is evident in VP1 protein levels of intracellular and in the culture supernatant over time, especially after 24 h post-infection." (PMID 39772852, 2025).
endocrine system disorder (1 paper, 2022). A disease involving the endocrine system. "In the gene group of endocrine system disorder, the most important gene was thyroid peroxidase (TPO), this gene was overexpressed, and the next genes carbonic anhydrase VI (CA6), caveolin protein 1 (CAV1), and solute carrier family type 12 (SLLC12A3) were underexpressed." (PMID 35059043, 2022).
peripheral neuropathy (1 paper, 2019). A disorder affecting the peripheral nervous system. "TSAs include anti-salivary protein 1 (SP1) and anti-carbonic anhydrase 6 (CA6) that are associated with early stages of pSS and worse ocular manifestations, and anti-calponin antibodies are more related to peripheral neuropathy." (PMID 31683641, 2019).
CA6 also shares sentences with these, for which no sentence is quoted: dry mouth (2 papers); kidney disorder (2); mouth (2); Zinc deficiency (2); Anosmia (1); atherosclerosis (1); bacterial infection (1); cardiac hypertrophy (1); connective tissue diseases (1); dilated cardiomyopathy (1); familial partial lipodystrophy (1); gastric ulcer (1); gastrointestinal disease (1); inflammatory bowel disease (1); interstitial lung disease (1); invasive breast carcinoma (1); kidney carcinoma (1); nutritional disease (1); pancreatic tumors (1); parotitis (1); renal cell carcinoma (1); respiratory diseases (1); rhabdomyosarcoma (1); viral infection (1).